MEG3 (maternally expressed 3)
Diseases named in the same sentence as MEG3 in open-access papers (continued):
Sharing a sentence is not in itself a finding about the gene and the disease.
neuroblastoma (continued). "In neuroblastoma and pheochromocytoma tissues, the aberrant methylation of the MEG3 promoter correlated with decreased MEG3 level in 25% and 10% of the cases, respectively." (PMID 29069869, 2017). "HCN3 and linc01105 exhibited the higher expression (P < 0.05; P < 0.01, respectively) in neuroblastoma tissue, whereas MEG3 displayed the lower expression (P < 0.01)." (PMID 27824082, 2016). "Consistent with the microarray results, the qRT-PCR analysis revealed that the expression levels of HCN3 (P < 0.05) and linc01105 (P < 0.01) were higher, whereas MEG3 expression was lower (P < 0.01), in neuroblastoma tissue compared to para-tumor tissue." (PMID 27824082, 2016). "Reduced MEG3 expression and promoter DNA hypermethylation has been observed in various human tumor types: pituitary adenomas, neuroblastomas, pheochromocytomas, Wilms tumors, and other carcinomas." (PMID 22666422, 2012). "The lncRNA MEG3 (maternally expressed 3) is found to be downregulated in neuroblastoma." (PMID 38473229, 2024). "The lncRNA MEG3 is considered to be an important tumor suppressor in neuroblastoma." (PMID 38891878, 2024). "Combined blockage of EZH2 and HDAC1 with the appropriate inhibitors may be an effective treatment strategy for neuroblastoma cases with low MEG3 and high EZH2 levels." (PMID 38473229, 2024). "The results showed that either the MEG3 polymorphism alone or in combination did not confer neuroblastoma susceptibility." (PMID 29615542, 2018). "Among neurologic tumors, in neuroblastoma (NB), lncRNA MEG3 functions as an anti-tumor agent, and overexpressing MEG3 in NB cells decreased epithelial-mesenchymal transition invasion and metastasis via mTOR signaling and inhibited FOXO1-mediated autophagy." (PMID 38933333, 2024). "This indicates that MEG3 may directly promote apoptosis in neuroblastoma cells." (PMID 35592755, 2022). "Additionally, several genetic alterations including MEG3 polymorphisms, ERCC1/XPF, and NRAS were associated with the occurrence of neuroblastoma and might serve as important diagnosis biomarkers in the future." (PMID 32695501, 2020). "However, neither of the two MEG3 polymorphisms was associated with neuroblastoma susceptibility, no matter adjusted for age and gender or not." (PMID 29615542, 2018). "In addition, loss of MEG3 expression was observed in the majority of nonfunctioning pituitary adenomas (NFPAs), neuroblastoma and renal cell carcinoma." (PMID 29069869, 2017). "A recent analysis revealed that MEG3 transcriptionally inhibits the expression of Nestin, a well-known CSC marker in neuroblastoma, potentially inhibiting CSC development." (PMID 38891878, 2024). "Summarizing both articles, reduced MEG3 levels and increased EZH2 levels form a feedback loop that promotes the development of neuroblastoma." (PMID 38473229, 2024). "The expressions of MEG3, HCN3 and linc01105 were all correlated negatively with the INSS neuroblastoma stage; low and high expressions of these genes were associated with early and late tumor stages, respectively." (PMID 27824082, 2016). "Taken together, MEG3 and EZH2 could in the future be joint targets for the treatment of childhood neuroblastomas." (PMID 33061817, 2020). "We identified MEG3, HCN3 and linc01105 as lncRNAs that are relevant to neuroblastoma." (PMID 27824082, 2016).
non-small cell lung carcinoma (25 papers, 2013 to 2025). A group of at least three distinct histological types of lung cancer, including non-small cell squamous cell carcinoma, adenocarcinoma, and large cell carcinoma. "Curcumin has also been linked to a higher level of MEG3 in ovarian cancer and in non-small cell lung carcinoma (NSCLC), which increases the sensitivity to cisplatin and reduces tumor growth, respectively." (PMID 40282449, 2025). "Maternally expressed gene 3 (Meg3) expression levels are significantly lower in non-small cell lung cancer (NSCLC)." (PMID 37240281, 2023). "In non-small cell lung cancer, up-regulation of MEG3 led to an increase in the apoptosis rate of cancer cells." (PMID 34199840, 2021). "The study was done to investigate the effect of LncRNA MEG3 on the immunity and autophagy of non-small cell lung carcinoma through the IDO signaling pathway." (PMID 34399782, 2021). "MEG3 overexpression has been shown to increase PTEN expression, while MEG3 knockdown decreased PTEN expression in gemcitabine-resistant non-small cell lung cancer cells." (PMID 34758851, 2021). "As a lncRNA, Maternally Expressed Gene 3 (MEG3) located on the human chromosome 14q32.3 has an inhibitory effect in a variety of cancers, such as bladder cancer, gastric cancer, and non-small cell lung cancer." (PMID 34199840, 2021). "MEG3 expression was decreased in non-small cell lung cancer (NSCLC) tumor tissues compared with normal tissues, and associated with advanced pathologic stage, and tumor size." (PMID 24098911, 2013). "Besides, compared with normal tissue, the expression of MEG3 is reduced in non-small cell lung cancer (NSCLC) tumor tissues." (PMID 37074188, 2023). "Some reports unfolded the regulation between lncRNA and microRNA in cancer therapy thoughIt was reported that MEG3 may enhance cisplatin sensitivity in non-small cell lung cancer through modulating miR-21." (PMID 31660855, 2019). "CUR induced apoptosis of gemcitabine-resistant non-small cell lung cancer (NSCLC) cell lines A549/GR and H520/GR and upregulated the expression of MEG3 and PTEN." (PMID 36552560, 2022). "LncRNA levels are strongly associated with aberrant gene expression that may drive cancer development and progression, such as HOTAIR in non-small cell lung cancer (NSCLC), PRNCR1 (also known as PCAT8) and PCGEM1 in prostate cancer, and MEG3 in cervical cancer and meningiomas." (PMID 25496320, 2014).
ischemic stroke (22 papers, 2017 to 2025). A stroke disorder caused by obstruction of blood flow to the brain, due to thrombotic (local blood clot formation) or embolic (due to a blood clot or other material traveling from another site) event. "And in other diseases such as IS (ischemic stroke), the signaling of MEG3/miR-181b, as well as the association between the polymorphisms located in MEG3/miR-181 and the risk of IS, was also investigated." (PMID 35422450, 2022). "Another study demonstrated that electroacupuncture ameliorates cognitive impairment and neurological damage in rats with ischemic stroke by regulating the MEG3/miR-4640-3p axis." (PMID 41551315, 2025). "Higher levels of MEG3 in ischemic stroke lead to the upregulation of GRB2 by binding to and inhibiting miR-378, resulting in the destruction of the Akt/mTOR pathway." (PMID 39021183, 2024). "Taken together, lncRNA MEG3 is overexpressed in ischemic stroke and promotes autophagy, thus, targeting MEG3 expression can attenuate ischemic stroke damage by inhibiting autophagy." (PMID 39021183, 2024). "Other lncRNAs, such as ANRIL, SNHG14, TUG1, and MEG3, were also found to affect neuronal apoptosis, inflammation and angiogenesis during ischemic stroke." (PMID 35677353, 2022). "For instance, the lncRNA MEG3 inhibits neuronal death and neurological problems in mice with ischemic stroke through the MEG3/miR-378/Grb2 axis and inhibits neuronal autophagy and neurodegeneration by silencing Grb2." (PMID 36671403, 2022). "MEG3 accelerates the ischemic stroke process by inhibiting miRNA 424–5p, which targets semaphorin 3A and activates the MAPK pathway." (PMID 36420646, 2022). "In this study, we mainly illustrated a mechanism of MEG3/miR-424-5p/Sema3A axis mediating ischemic stroke." (PMID 32065781, 2020). "In contrast, lncRNA MEG3 negatively regulated angiogenesis after ischemic stroke via suppressing the Notch pathway, and the silencing of MEG3 resulted in a proangiogenesis effect in vascular endothelial cells." (PMID 32190702, 2020). "Recently, the function and expression of MEG3 in the neural system and ischemic stroke were discovered." (PMID 29449542, 2018). "Furthermore, an in vivo model of ischemic stroke revealed that the knockdown of MEG3 not only inhibited the activation of autophagy but also reduced infarct size and ameliorated behavioral deficits." (PMID 39021183, 2024). "There is growing evidence that lncRNA MEG3 expression is dysregulated during various diseases, including cancers, Huntington's disease, Parkinson's disease, cardiovascular diseases, bone diseases, and ischemic stroke." (PMID 39021183, 2024). "In addition, MEG3 can inhibit the proliferation of neural stem cells after ischemic stroke via positive regulation of miR-493-5p." (PMID 35761379, 2022). "Notably, ischemic stroke samples displayed heightened expression of lncRNA MEG3 and Sema3A and reduced expression of miR-424-5p." (PMID 33192490, 2020). "Meanwhile, MEG3 may play a vital role in other activities, such as repairing processes of bone marrow derived mesenchymal stem cells and angiogenesis after ischemic stroke." (PMID 31660855, 2019). "So, it is the first report to determine the interaction of MEG3–miR-21–PDCD4 in ischemic stroke." (PMID 29238035, 2017). "Furthermore, MEG3 was significantly decreased after ischaemic stroke, and overexpression of Meg3 could decrease the capillary density after ischaemic stroke via inhibition of notch signalling." (PMID 29392896, 2018). "A previous study was performed on the plasma samples from patients with ischemic stroke, and up-regulated levels of lncRNAs including H19, MIAT, ANRIL, MEG3 and NEAT1 were detected." (PMID 33613191, 2020).
acute myeloid leukemia (21 papers, 2012 to 2023). Acute myeloid leukemia (AML) is a group of neoplasms arising from precursor cells committed to the myeloid cell-line differentiation. "In a genetic profiling study of acute myeloid leukemia patients, hypermethylation of the imprinted gene MEG3 was linked to significantly reduced survival." (PMID 31379598, 2019). "The level of MEG3 promoter region (MEG3-DMR) methylation is associated with OS of acute myeloid leukemia (AML) patients with myelodysplastic syndrome (MDS)." (PMID 29069869, 2017). "However, one study reported this miRNA is associated with expression of the long non-coding RNA MEG3 in acute myeloid leukemia." (PMID 34048164, 2021). "The promoter of MEG3, which encodes the long non-coding RNA (lncRNA) MEG3, is often hypermethylated in acute myeloid leukemia (AML)." (PMID 28407691, 2017). "A previous study indicated that ALG9 was regulated by lncRNA MEG3 and participated in the drug resistance mechanism in acute myeloid leukemia." (PMID 35782861, 2022). "There have identified a number of lncRNAs association with several subtypes of leukemia, such as MEG3, IRAIN, and UCA1 related to acute myeloid leukemia (AML) and ANRIL, LUNAR1, in ALL." (PMID 34101758, 2021). "Accumulating evidence implicates the imprinted genes from this locus, DLK1 and MEG3, in the development and progression of acute myeloid leukemia (AML)." (PMID 30876483, 2019). "The study found that MEG3 in acute myeloid leukemia (AML) in the expression significantly decreased, but its influence on the biological behavior of AML tumors is still unclear." (PMID 29029424, 2017). "Hypermethylation in 43 patients with myelodysplastic syndrome and 42 cases of acute myeloid leukemia patients were 34.9% and 47.6% of the patients with MEG3 promoter, further found that hypermethylation of MEG3 promoter in patients with poor prognosis." (PMID 29029424, 2017). "We found that two lncRNAs including MEG3 and H19 are up-regulated in acute myeloid leukemia (AML) cancer compared to normal blood cells (Fold change > 1.5, P-value < 0.01)." (PMID 24312125, 2013). "And hypermethylation of MEG3 promotor was also discoverable among patients who were tortured by neurofibroma, meningioma, myelodysplastic syndrome, acute myelogenous leukemia, and acute myeloid leukemia." (PMID 32618397, 2020). "In Acute Myeloid Leukemia, TET2 can activate lncRNA MEG3 transcription." (PMID 36969033, 2023). "Moreover, MEG3, UCA1, and H19 are upregulated in acute myeloid leukemia." (PMID 26448935, 2015).
Obesity (21 papers, 2010 to 2025). Accumulation of substantial excess body fat. "A SNP residing in DLK1 that showed paternal polar overdominance for human obesity is a maternal eQTL of MEG3, offering an explanation for the baseline risk of homozygous samples through association between MEG3 expression and obesity." (PMID 40502026, 2025). "While some reports suggest that MEG3 knockdown promotes adipocyte differentiation, indicating potential context-dependent functions, our data solidify its association with human obesity." (PMID 41199597, 2025). "The results also accentuate circulating MEG3/miR-27a/IGF1/IGFBP3 as valuable markers of the early detection of obesity-related CRC, with miR-27a is associated with its risk." (PMID 38704452, 2024). "It has been revealed that the expression of endothelial MEG3 is elevated in obesity, and knockdown of MEG3 causes cellular senescence in human umbilical vein endothelial cells (HUVECs) and hepatic endothelium in obese mice." (PMID 35207562, 2022). "We earlier reported that obesity was associated with lower methylation at the MEG3, SNRPN, and SGCE/PEG10 DMRs, and increased DNA methylation at MEG3-IG and H19 DMRs." (PMID 33494820, 2021). "We have previously demonstrated that Meg3 deficiency induced the DNA damage response and cellular senescence in human umbilical vein endothelial cells and caused obesity-induced insulin resistance by promoting the cellular senescence of hepatic endothelium in obese mice." (PMID 38518516, 2024). "Researchers have suggested that the manipulation of MEG3 expression may represent a novel approach to managing obesity-associated hepatic endothelial senescence and IR." (PMID 34298896, 2021). "Furthermore, this confirms that the identified DNA methylation changes at MEG3-IG DMR are linked to obesity since they also occur in fertile males." (PMID 31246962, 2019). "Emerging studies in both animal models and humans have begun to elucidate the molecular mechanisms of the lncRNA MEG3 in obesity and obesity-related diseases." (PMID 40806129, 2025). "Our results show an elevated expression of MEG3 in children with obesity, which is consistent with recent findings reporting elevated expression of MEG3 in the serum of children with obesity." (PMID 40806129, 2025). "This study evaluated MEG3, FTO, and ATF4 expression in PBMCs from children with obesity and their associations with added sugar intake and lipid metabolism genes." (PMID 40806129, 2025). "Accordingly, the present study aimed to evaluate the expression of MEG3, FTO, and ATF4 in PBMCs from children with obesity and to assess their associations with added sugar intake and the expression of lipogenesis-related genes." (PMID 40806129, 2025). "Long non-coding RNAs, particularly MEG3, are involved in obesity through regulation of lipogenic genes including ATF4, FTO, SREBP1, FASN, and ACACA." (PMID 40806129, 2025). "Conversely, our study found a positive correlation between FTO and MEG3 expression in PBMCs from children with obesity." (PMID 40806129, 2025). "As long non-coding RNAs maternally expressed gene 3 (Meg3) prevents cellular senescence of hepatic vascular endothelium and obesity-induced insulin resistance, we decided to examine its role in cellular senescence and atherosclerosis." (PMID 38518516, 2024). "Meg3 levels have previously been shown to be low in obesity, and our results concur with the earlier finding that showed the role of Meg3 in glucose homeostasis and insulin signaling." (PMID 39596898, 2024). "Nevertheless, our bioinformatics analysis findings portrayed the possible interactions of MEG3 and its studied downstream targets with each other and with glucose that confirms their relation to insulin resistance, obesity, and metabolic reprogramming." (PMID 38704452, 2024). "Subsequently, the association of MEG3 rs941576 with CRC risk in stratified groups according to sex, age, and obesity was assessed." (PMID 38704452, 2024).